DEFB107B (defensin beta 107B)
Description:
Has antibacterial activity.
Synonyms: HsT21816
Gene: Protein-coding gene on chromosome 8 (7,495,911 to 7,509,311, forward strand). Ensembl gene ENSG00000198129.
Subcellular location: Secreted
Pathways (Reactome):
Immune System: Beta defensins; Defensins
Gene Ontology:
Molecular function: lipid binding
Biological process: defense response to Gram-negative bacterium; defense response to Gram-positive bacterium; innate immune response
Cellular component: extracellular region
Homologues: Orthologues: chimpanzee DEFB107A (96% identical), dog CBD107 (63% identical), rat Defb13 (49% identical), mouse Defb13 (46% identical). Paralogues in human: DEFB107A (100% identical).